FOXP3 (forkhead box P3)
Diseases named in the same sentence as FOXP3 in open-access papers (continued):
Sharing a sentence is not in itself a finding about the gene and the disease.
cancer (921 papers, 2006 to 2026). A tumor composed of atypical neoplastic, often pleomorphic cells that invade other tissues. "Deconvolution of bulk RNA sequencing (RNA-seq) data reveals high content at baseline in cancer cells, immunosuppressive cancer-associated fibroblasts, FOXP3+ CD4+ regulatory T lymphocytes, and TREM2+ macrophages." (PMID 41519129, 2026). "Several polymorphisms in immune-regulatory genes, including PD-1 rs36084323, PD-L1 rs822336 and rs4143815, PD-L1 copy number variation (CNV), FOXP3 rs3761548 and rs2232365, and miR-155 rs767649, have been implicated in cancer susceptibility and prognosis." (PMID 40806346, 2025). "High intratumoral FOXP3+ Tregs are consistently associated with poor prognosis in various cancers due to their immunosuppressive activity." (PMID 41150760, 2025). "mIF analysis revealed significantly increased infiltration of FOXP3+ regulatory T cells (Treg) and cancer-associated fibroblasts (CAFs) in the APE1-high group." (PMID 41235229, 2025). "This confirms earlier observations that FOXP3 expression is associated with development, progression and prognosis of cancers." (PMID 40365511, 2025). "This is in contrast with the general association of FoxP3+ regulatory T-cells (Tregs) with immune evasion and cancer progression in HNSCC." (PMID 41511327, 2025). "Increased levels of CD68 + and CD4 + FOXP3 + cells (above the 75th percentile) were linked to worse cancer-specific survival (CSS) in patients with ccRCC." (PMID 39751643, 2025). "Previous studies have explored the interaction between cancer risk and the polymorphism of Foxp3 gene." (PMID 39935826, 2025). "The presence of FOXP3+ CD8+ Tregs is associated with cancer prognosis, with elevated levels potentially correlating with a poorer clinical outcome." (PMID 41280919, 2025). "Diagnostic ROC curve indicated that FOXP3 has good accuracy in distinguishing between cancer and adjacent normal tissues, with an AUC of 0.781." (PMID 39883234, 2025). "The FOXP3 rs3761548 A allele was also revealed as risk factor in the majority of different cancer types related to reduced FOXP3 expression in blood cells." (PMID 39000267, 2024). "Consistent with our observations, these sub-TMEs, associated with the basal-like subtype cancer cells, demonstrated increased expression of markers for FOXP3+ Tregs and CD206+ M2 macrophages." (PMID 38733987, 2024). "Both gene expressions were closely associated with ARG1 expression and FoxP3 expression, respectively, in cancer str of the CRC tumors." (PMID 38557819, 2024). "In fact, there have been reports that high infiltration of Foxp3 + TILs in the TME is associated with an unfavorable prognosis in patients with many types of cancers." (PMID 38402536, 2024). "Several FOXP3 single-nucleotide polymorphisms (SNPs) were detected and its role in cancer susceptibility was investigated." (PMID 38674427, 2024). "The association of three FOXP3 functional SNPs (rs3761548, rs3761549 and rs2280883) and cancer risk was performed by an updated meta-analysis." (PMID 38674427, 2024). "FOXP3 is reported to be implicated in tumorigenesis in many cancer types acting either as a transcriptional activator or tumor-suppressor gene." (PMID 39000267, 2024). "Fusobacterium was positively associated with the expression of RorγT and FoxP3 in cancer samples; however, their expression was associated distinctively in precancer samples." (PMID 37409975, 2023). "PGE2 secreted from cancer cells is associated with increased FOXP3 expression in Treg cells, a key component of the immune-suppressive environment." (PMID 37560473, 2023).
cancer (continued). "Previous studies have suggested the controversial role and inconsistency of FOXP3 gene polymorphisms to disease susceptibility in various cancers 21, 39-41." (PMID 37215447, 2023). "For the associations between the FOXP3 rs3761548 polymorphisms and cancer risk, most studies have associated the A allele or the AA genotype of rs3761548 with increased cancer susceptibility, disease progression, and poor prognosis 20, 41, 46-50." (PMID 37215447, 2023). "The marker Forkhead box P3 (FoxP3), typically associated with Tregs, is also expressed by certain cancer cells." (PMID 38022609, 2023). "A direct association of CD47 expression by cancer cells and the % FOXP3+ TILs (p = 0.01, r = 0.25) and with the FIL-score (p = 0.004, r = 0.28) was noted in linear regression analysis." (PMID 35406573, 2022). "Increased FOXP3+ Treg cells have also been linked to a higher risk of metastasis in other cancers, including breast, ovarian, prostate, thyroid, gastric, colorectal, and skin cancers." (PMID 36569832, 2022). "In a meta-analysis of 15,512 cancer patients in 76 studies, high FoxP3+Treg infiltration was associated with shorter OS in many solid tumors but with improved OS in colorectal, esophageal, and HNSCC15." (PMID 36581686, 2022). "FOXP3 polymorphisms were associated with various disorders, including cancer, and certain SNPs have been reported to have functional impacts on immunological tolerance mediated by Treg cells." (PMID 36083385, 2022). "On the other hand, the protein levels of TGF-β, SMAD2/3, TGFBR1, and pSMAD1/5/9 in cancer stromal cells were positively associated with FOXP3+ T cell infiltration but negatively associated with CD8+ T cell infiltration." (PMID 36458816, 2022). "Although there are controversial reports, the frequency of FOXP3+ Treg cells in most cancers has been associated with a worse prognosis." (PMID 36038861, 2022). "A direct association of CD47 expression by cancer cells and the % FOXP3+ TILs (p = 0.01, r = 0.25) was also noted." (PMID 35406573, 2022). "The levels of FOXP3+ Treg cells are strongly associated with cancer metastasis in various human cancers." (PMID 36569832, 2022). "The promoter region of the FOXP3 gene contains five SNPs; among them, the rs3761548C/A and rs3761549C/T gene, with have been implicated to be associated with cancer risk." (PMID 36083385, 2022). "Increasing evidence points towards CD4+CD25+Foxp3+ Tregs having a pathogenic role in cancer development and metastasis, primarily through inhibiting host cancer-associated-antigen adaptive immunity." (PMID 34831195, 2021). "High Klintrup–Mӓkinen grade and low GMS have both been associated with improved survival, with Klintrup–Mӓkinen being associated with increased levels of CD3, CD8 and FoxP3 and reduced cancer recurrence, propagating a positive association." (PMID 33338327, 2021). "Forkhead box P3 (FOXP3) is a protein involved in the immune system response, and the expression of FOXP3 has been reported to be associated with poor prognosis in several cancers." (PMID 33952249, 2021). "The D8/FOXP3 T cell ratio is reported to be lower (P = 0.062) in cancer-associated areas that are known to be associated with cancer progression and represents a pro-fibrotic stroma element." (PMID 33809111, 2021). "The increased number of Tregs, especially the FOXP3+ ones, has been applied as an independent risk factor of cancer relapse for their roles in immunity tolerance." (PMID 34113647, 2021). "It was associated with an increased frequency and absolute number of CD4+Foxp3+T regulatory (Treg) cells, an immunosuppressive cell which is frequently associated with poor prognosis in cancer." (PMID 32823603, 2020). "FOXP3, which is a common immunohistochemical marker for Tregs, has been confirmed to be closely associated with the prognosis of patients with cancer." (PMID 33062072, 2020). "In cancer, increased numbers of Treg cells, and therefore high FOXP3 expression, is associated with poor prognosis." (PMID 33396954, 2020).
cancer (continued). "Another T cell type that has diagnostic and prognostic value in different types of cancer is regulatory T cells, expressing FOXP3." (PMID 32884895, 2020). "Since new case–control studies and more polymorphisms were published in recent years, we conducted a comprehensive search of relevant studies with the aim to better clarify the association between FOXP3 polymorphisms and cancer susceptibility." (PMID 30782783, 2019). "The role of forkhead box P3 (FOXP3) protein in tumorigenesis has long been controversial and existing data on the association between FOXP3 gene polymorphisms and cancer susceptibility were inconsistent." (PMID 30782783, 2019). "On the contrary, FoxP3+ regulatory T lymphocytes (Tregs) are supposed to mediate immune tolerance and associated with therapeutic failure and poor cancer survival." (PMID 31138162, 2019). "This meta-analysis suggested that FOXP3 rs3761548 (A/C) polymorphisms were associated with increased cancer risk in Chinese population while rs2280883 (C/T) and rs3761549 (T/C) polymorphisms were not." (PMID 30782783, 2019). "In our further screening, 82 articles were excluded for duplicity while 104 articles were removed since they were irrelevant to FOXP3 polymorphisms or cancer risk according to titles and abstracts." (PMID 30782783, 2019). "It was found that high FoxP3+-Treg infiltration was linked to an improvement in cancer-specific survival." (PMID 30621735, 2019). "The balance between FOXP3+ and CD8+ T-cells is another clinically linked parameter, as low-FOXP3/ high-CD8+ ratios have been linked with positive survival effects across multiple cancer types including NSCLC." (PMID 29874226, 2018). "Upregulation of FOXP3 is associated with inhibition of cell growth in solid tumor cell lines from breast, prostate, epithelial ovarian and gastric cancer." (PMID 30103821, 2018). "Few papers correlated the two ligands to CD4+CD25+Foxp3+ expansion in inflammation and in pancreatic tumors, thus suggesting Jagged as an important area of investigation in cancer-associated Tregs." (PMID 30364244, 2018). "Increased Foxp3 Treg infiltration has been known to be associated with worse clinical outcomes and various poor prognostic factors in many cancers." (PMID 28669079, 2018). "A recently concluded meta-analysis demonstrated that FOXP3+ Treg infiltrates were predominantly associated with worse OS in a review of over 17 types of cancer." (PMID 29276510, 2017). "In previous studies with different types of cancer, the presence of FOXP3+ cells has been associated with both poor and improved OS, although mRNA expression levels were not assessed in any of these studies." (PMID 27463005, 2016). "In early reports high numbers of FoxP3+ cells in cancer were associated with an unfavourable prognosis potentially by inhibiting an effective anti-tumoural immunoreaction." (PMID 27494875, 2016). "It is essential in neurogenesis and the maintenance of dopaminergic neurons, plays a role in the activation of FOXP3 in regulatory T cells and in their differentiation and function and has been associated with various types of cancer." (PMID 26576536, 2015). "We did a meta-analysis to assess the prognostic effect of FoxP3+ Treg across different types of cancer and to investigate factors associated with variations in this effect." (PMID 26462617, 2015). "Epidemiological studies suggest that the FOXP3 promoter polymorphisms, rs3761549 and rs376154, are associated with the cancer risk." (PMID 25364468, 2014). "Epidemiological studies have been conducted to investigate the association between the FOXP3 promoter polymorphisms, rs3761549 and rs3761548, and the risk of cancer." (PMID 25364468, 2014). "The infiltration of tumors by regulatory T cells (defined as FOXP3+ TILs) has been reported to be associated with patient survival in a variety of cancers, but its prognostic value remains controversial." (PMID 25193543, 2014).
cancer (continued). "The infiltration of FOXP3+ regulatory T cells into invasive tumors has been reported to be associated with survival in a variety of cancers." (PMID 25193543, 2014). "In conclusion, despite the fact that the sample size in this cohort is small to draw definitive conclusions, our study shows for this first time that high Foxp3 expression in cancer cells is associated with a dismal prognosis in CRC." (PMID 23382847, 2013). "For a number of years, Foxp3 expression has been exclusively linked to the T cell lineage, but, recently, Foxp3 has been reported to be expressed in a variety of cancer cell lines." (PMID 24179494, 2013). "Those patients with high Foxp3+ expression profile in cancer cells were associated with a poorer prognosis than patients with low expression profile of Foxp3+ in their cancer cells." (PMID 23382847, 2013). "High Foxp3 expression of the cancer cells was associated with poor prognosis compared to patients with low Foxp3 expression." (PMID 23382847, 2013). "Because LCK enhances uPA and MMP9 expression resulting in cancer invasion and metastasis, the effect of FOXP3 WT and Y342F mutation on LCK-induced invasion was investigated." (PMID 24155921, 2013). "We were unable to find any association between CD4, CD8 or Foxp3+ (presumed Tregs) and cancer recurrence or with other clinico-pathological variables." (PMID 21864372, 2011). "There are increasing evidences that cancer cells-derived soluble factors promote the induction of tolerance through the generation of CD4+ α chain of IL-2R (CD25)+ forkhead box P3 (Foxp3)+ Treg subset, which is linked to compromised antitumor immune responses." (PMID 21922022, 2011). "to be associated with a reduction in immunosuppressive Tregs and FOXP3+ cancer cells." (PMID 41486497, 2026). "Given that P2X7 is a major positive regulator of the NLRP3 pathway, it is tempting to speculate that at list part of Foxp3 positive cells could belong to the subclass of Foxp3+ RORγt + IL17+ cells which were recently associated with NLRP3 activation in cancer." (PMID 40759630, 2025). "However, the FOXP3 to cytotoxic T-cells ratio was significantly higher in BRCA-mutated cancer, implying a more immunosuppressed TME." (PMID 40427006, 2025). "Tregs, a subset of CD4+T cells expressing Foxp3, play critical roles in suppressing immune responses and migrating toward tumors in the presence of chemokines to suppress antitumor immune responses, causing cancer cells to grow and proliferate." (PMID 40563656, 2025). "Moreover, alterations in Foxp3 expression or function have been implicated in various autoimmune diseases and cancers." (PMID 40650089, 2025). "The findings above suggest that the influence of Foxp3 polymorphisms on cancer susceptibility may vary significantly between different types of cancer." (PMID 39935826, 2025). "Female cancer cells commonly have heterozygous FOXP3 and WTX deletions or mutations." (PMID 38827026, 2024). "Despite the fact that FOXP3+ T cells, as regulatory T cells, can inhibit effective immune responses against cancer cells, recent studies have suggested that FOXP3+ T cells may be associated with favorable prognosis." (PMID 39259184, 2024). "From a molecular perspective, we sought to assess how these agents influence the cellular mechanisms associated with immune regulation and cancer cell survival, specifically through the modulation of FOXP3, a key transcription factor involved in immune suppression." (PMID 39770446, 2024). "CD8 and FOXP3 densities in biopsies were significantly associated with cancer-specific survival." (PMID 39444424, 2024). "Furthermore, numerous clinical investigations have established that overexpression of Foxp3 is associated with a poor prognosis and low survival rate in cancer patients." (PMID 38919615, 2024). "Interestingly, our study indicates that FOXP3 has the strongest association with CD47, and infiltration of FOXP3 cells is correlated with poor prognosis in several cancers." (PMID 36598153, 2023).
cancer (continued). "FoxP3+ Treg cells with an activated phenotype can be enriched in tumors in comparison with peripheral blood and are associated with a poor prognosis in patients with various types of cancer, including cervical, renal, melanomas, and breast cancers." (PMID 37529610, 2023). "FOXP3+ TILs are known to disrupt antitumor immunity by suppressing the effector functions of various immune cells and have been implicated in the escape of cancer cells from immunosurveillance." (PMID 37835488, 2023). "A direct association of CD47 expression by cancer cells and the % FOXP3+ TILs was also noted." (PMID 35406573, 2022). "This FOXP3 marker was known to be a marker of T regulatory cells, an important T cells subset that work to suppress inflammation and has been implicated to promote cancer immune escape in multiple cancer." (PMID 35963999, 2022). "Additionally, the presence of FoxP3+ T lymphocyte infiltrates were associated with poor prognosis in different types of cancers, including breast, lung, pancreatic, ovarian, and cervical cancers." (PMID 34440038, 2021). "However, it has also been reported that infiltration of CD4+Foxp3+ T-cells is associated with a favorable prognosis in some types of cancers." (PMID 34647108, 2021). "The MYC oncogene causes many human cancers and is activated by FOXP3 in NSCLC." (PMID 34503105, 2021). "Therefore, further investigation on different sets of the population with a larger sample size is required to establish FOXP3 as a potential cancer biomarker for diagnostic and prognostics purposes." (PMID 34938323, 2021). "In turn, it is conceivable that protective Foxp3 alleles may also enhance the effectiveness of immunotherapies for cancer." (PMID 31729760, 2020). "The identification of such human Foxp3 variants may guide cancer prognostics and therapeutic strategies." (PMID 31729760, 2020). "Three types of FOXP3 polymorphisms and six types of cancers were analyzed." (PMID 30782783, 2019). "Three FOXP3 polymorphisms and six cancer types were evaluated." (PMID 30782783, 2019). "In addition, as previously reported, only FOXP3+ Treg cell infiltration in cancer nests was associated with poor prognosis." (PMID 31118034, 2019). "FoxP3 is the key regulatory transcription factor for Treg cells, and mutations in the FoxP3 gene result in severe autoimmune disorders and the onset and progression of various cancers." (PMID 30893948, 2019). "Polymorphisms of the FOXP3 gene may change FOXP3 protein quantitatively or functionally, thus contributing to predisposition and progression of cancer." (PMID 30782783, 2019). "The re-localization of FOXP3 protein due to polymorphisms like rs3761548 in certain types of cancer might affect transcription functions and thus cytokine production of Tregs." (PMID 30782783, 2019). "This reminded us the complex role of FOXP3 and raised the possibility that mutations of FOXP3 gene might cause immune dysregulation and further cancer development." (PMID 30782783, 2019). "Several FOXP3 SNPs have been unveiled and their role in cancer susceptibility was explored." (PMID 30782783, 2019). "Recent studies have shown that FOXP3 is associated with growth inhibition of cancer cells." (PMID 30103821, 2018). "Thus, it can be explained that in our study high expression of FOXP3 in cancer cells was associated with prolonged OS." (PMID 28029650, 2017). "It is assumed that FOXP3 may generally have a suppressive role but appears as a favorable prognostic marker in some cancers because of its association with CD8+ T cells." (PMID 28851300, 2017). "However, inclusion of studies that analyzed FOXP3 alone or in combination with other markers showed that global survival was significantly associated with cancer." (PMID 28603524, 2017). "FOXP3 genetic polymorphisms have been associated with cancer development and prognosis." (PMID 28713192, 2017).